Y_RNA (Y RNA )
Gene: Miscellaneous RNA gene on chromosome 3 (101,955,077 to 101,955,185, forward strand). Ensembl gene ENSG00000202177.
Homologues: Orthologues: chimpanzee Y_RNA (99% identical), macaque Y_RNA (85% identical). Paralogues in human: Y_RNA (87% identical), RNY1P11 (86% identical), Y_RNA (86% identical), RNY1 (85% identical), Y_RNA (85% identical), Y_RNA (84% identical), Y_RNA (83% identical), Y_RNA (82% identical), RNY1P15 (81% identical), Y_RNA (81% identical), RNY1P8 (80% identical), Y_RNA (80% identical), and 94 more.